AMDHD1 (amidohydrolase domain containing 1)
Description:
Catalyzes the hydrolytic cleavage of the carbon-nitrogen bond in imidazolone-5-propanoate to form N-formimidoyl-L-glutamate. This reaction represents the third step of the universal histidine degradation pathway. In addition to its metabolic role, functions as a tumor suppressor by promoting TGF-beta signaling. Mechanistically, inhibits ubiquitination and proteasomal degradation of SMAD4, thereby stabilizing the protein. Enhances SMAD2/3 phosphorylation and increases TGF-beta-dependent transcriptional responses. Consequently, promotes apoptosis and induces cell cycle arrest in tumor cells.
Synonyms: HMFT1272; MGC35366
Tractability: Antibody: the Human Protein Atlas places it where antibodies can reach. PROTAC: ubiquitination databases record sites on it.
Gene: Protein-coding gene on chromosome 12 (95,943,301 to 95,968,720, forward strand). Ensembl gene ENSG00000139344.
Subcellular location: Cytoplasm
Subcellular location (Human Protein Atlas): Cytosol; Nucleoplasm; Plasma membrane
Pathways (Reactome):
Metabolism: Histidine catabolism
Gene Ontology:
Molecular function: protein binding; hydrolase activity, acting on carbon-nitrogen (but not peptide) bonds, in cyclic amides; imidazolonepropionase activity; hydrolase activity; hydrolase activity, acting on carbon-nitrogen (but not peptide) bonds
Biological process: L-histidine catabolic process
Cellular component: cytosol; cytoplasm
Genetic constraint (gnomAD): Loss-of-function variants: 36 observed, 34.42 expected, observed/expected ratio (o/e) 1.05, 90% interval 0.8 to 1.38. The upper end of that interval is the gene's LOEUF score, 1.38, which puts it in group 5 of 6, group 1 being the genes least tolerant of losing a copy. Missense variants: 542 observed, 496.74 expected, observed/expected ratio (o/e) 1.09, 90% interval 1.02 to 1.17. Synonymous variants: 190 observed, 187.48 expected, observed/expected ratio (o/e) 1.01, 90% interval 0.9 to 1.14.
Homologues: Orthologues: chimpanzee AMDHD1 (99% identical), rabbit AMDHD1 (91% identical), dog AMDHD1 (89% identical), macaque AMDHD1 (89% identical), mouse Amdhd1 (89% identical), pig AMDHD1 (89% identical), rat Amdhd1 (88% identical), guinea pig AMDHD1 (87% identical), tropical clawed frog amdhd1 (76% identical), zebrafish amdhd1 (72% identical), Caenorhabditis elegans amdh-1 (47% identical).
Diseases named in the same sentence as AMDHD1 in open-access papers:
AMDHD1 is named in the same sentence as 18 diseases in open-access papers, as found by Europe PMC text mining. Sharing a sentence is not in itself a finding about the gene and the disease. The quoted sentences say what the papers report.
breast carcinoma (2 papers, 2022 to 2025). "AMDHD1, the gene product is a protein which uses Zn and Fe as co-factors and has recently been suggested to play a protective role against breast cancer risk, and it is correlated to Vitamin D levels." (PMID 35163690, 2022).
adrenal adenoma (1 paper, 2020). "AMDHD1 has been reported to be overexpressed in adrenal adenoma compared with adrenal carcinoma and is involved in the histidine metabolism pathway." (PMID 32649057, 2020).
atypical lipomatous tumor (1 paper, 2018). An intermediate, locally aggressive lipomatous neoplasm. "Mutations in AMDHD1 are found to be associated with atypical lipomatous tumor, a cancer of connective tissues that resemble fat cells." (PMID 29343764, 2018).
Cirrhosis (1 paper, 2023). A chronic disorder of the liver in which liver tissue becomes scarred and is partially replaced by regenerative nodules and fibrotic tissue resulting in loss of liver function. "Therefore, it is speculated that AMDHD1 could aid in preventing liver fibrosis and cirrhosis among patients with NAFLD." (PMID 37697333, 2023).
colorectal cancer (1 paper, 2012). A primary or metastatic malignant neoplasm that affects the colon or rectum. "For the remaining genes more distant and sporadic associations have been mined in the literature for relevant diseases or other types of cancer, e.g. AMDHD1 and PHACTR1 have been linked to tobacco use disorders or RPRM with colorectal cancers." (PMID 23173873, 2012).
hepatocellular carcinoma (1 paper, 2023). A malignant tumor that arises from hepatocytes. "A study performed with integrated proteomics and bioinformatic analysis showed that AMDHD1 could predict the prognosis of patients with hepatocellular carcinoma (HCC)." (PMID 37697333, 2023).
muscular dystrophy (1 paper, 2020). Muscular dystrophy (MD) refers to a group of more than 30 genetic diseases characterized by progressive weakness and degeneration of the skeletal muscles that control movement. "The QTL on BTA5 which contained the AMDHD1 gene, was located close to a QTL previously associated with carcass composition, whereas the QTL on BTA11 contains DYSF, a gene known to be linked with muscular dystrophy in humans." (PMID 32000665, 2020).
pancreatic adenocarcinoma (1 paper, 2025). "Moreover, the association between low AMDHD1 expression and poorer OS was also observed in other cancer types, including kidney renal clear cell carcinoma, liver hepatocellular carcinoma, pancreatic adenocarcinoma (PAAD), sarcoma, skin cutaneous melanoma and uveal melanoma." (PMID 39143229, 2025).
cancer (3 papers, 2012 to 2025). A tumor composed of atypical neoplastic, often pleomorphic cells that invade other tissues. "The GEPIA database indicated the lower expression of AMDHD1 in various types of cancer and particularly the mRNA expression of AMDHD1 was notably down-regulated in CCA compared with normal bile duct tissues." (PMID 39143229, 2025). "The findings collectively suggest that AMDHD1 can activate the apoptotic pathway in CCA cells, underscoring its potential significance in cancer biology." (PMID 39143229, 2025).
tumor (1 paper, 2025). "Although recent studies have implicated AMDHD1 in tumor formation, its role in CCA development has been insufficiently explored." (PMID 39143229, 2025). "Additionally, low AMDHD1 expression was associated with adverse clinical characteristics such as poor tumor differentiation, presence of perineural invasion, elevated CA19-9 levels and advanced TNM stage." (PMID 39143229, 2025). "We also demonstrated that overexpression of AMDHD1 hindered G1/S progression in the cell cycle and promoted apoptosis, thereby inhibiting tumor growth and metastasis." (PMID 39143229, 2025). "As anticipated, we observed that the inhibition of tumor growth induced by overexpression of AMDHD1 was reversed after SMAD4 depletion." (PMID 39143229, 2025). "Results from xenograft models indicated that AMDHD1 overexpression significantly reduced tumor growth rates and resulted in lower tumor weights in the AMDHD1-OV group compared with controls at the study’s conclusion." (PMID 39143229, 2025). "Our findings position AMDHD1 as a pivotal prognostic marker and tumor suppressor, offering a novel therapeutic avenue through the combined targeting of AMDHD1 and SMAD4 in CCA." (PMID 39143229, 2025). "Considering the supportive role of AMDHD1 in TGF-β signaling, deletions and mutations of AMDHD1 in CCA could impair the tumor-suppressive functions of TGF-β signaling, thereby contributing to tumorigenesis." (PMID 39143229, 2025). "Our study identifies AMDHD1 as a significant prognostic biomarker and a tumor suppressor in CCA." (PMID 39143229, 2025). "The protein expression of SMAD4 was upregulated in the tumor tissues of the AMDHD1-OV group." (PMID 39143229, 2025). "We further demonstrated that overexpression of AMDHD1 significantly inhibited proliferation and migration of CCA cells in vitro, and curtailed tumor growth and metastasis in vivo." (PMID 39143229, 2025). "Complementary analyses involving RT-qPCR on 25 pairs of fresh tumor specimens and western blot analysis on 12 pairs of tumor specimens from PUMCH confirmed the decreased mRNA and protein expression levels of AMDHD1 in CCA tissues." (PMID 39143229, 2025).
AMDHD1 also shares sentences with these, for which no sentence is quoted: adrenal carcinoma (1 paper); cholangiocarcinoma (1); hematopoietic cancer (1); liver fibrosis (1); sarcoma (1); skin cutaneous melanoma (1); tobacco use disorders (1); uveal melanoma (1).